RNASE9 (ribonuclease A family member 9 (inactive))
Description:
Does not exhibit any ribonuclease activity.
Synonyms: h461; RAK1; HEL128
Tractability: Antibody: UniProt places it where antibodies can reach, with high confidence; UniProt predicts a signal peptide or a membrane-spanning region; its Gene Ontology location is reachable by antibodies, with medium confidence.
Gene: Protein-coding gene on chromosome 14 (20,556,093 to 20,561,047, reverse strand). Ensembl gene ENSG00000188655.
Subcellular location: Secreted
Gene Ontology:
Molecular function: RNA nuclease activity; nucleic acid binding
Biological process: defense response to Gram-positive bacterium
Cellular component: extracellular region
Genetic constraint (gnomAD): Missense variants: 259 observed, 254.63 expected, observed/expected ratio (o/e) 1.02, 90% interval 0.92 to 1.13. Synonymous variants: 92 observed, 89.79 expected, observed/expected ratio (o/e) 1.02, 90% interval 0.87 to 1.22.
Homologues: Orthologues: chimpanzee RNASE9 (95% identical), macaque RAK2 (80% identical), macaque RNASE9 (80% identical), macaque RNASE9 (79% identical), dog RNASE9 (44% identical), rat Rnase9 (32% identical), mouse Rnase9 (31% identical). Paralogues in human: RNASE6 (17% identical), RNASE7 (17% identical), RNASE1 (16% identical), RNASE12 (16% identical), RNASE3 (16% identical), RNASE4 (16% identical), RNASE10 (15% identical), RNASE2 (15% identical), RNASE8 (15% identical), RNASE13 (15% identical), RNASE11 (14% identical), ANG (13% identical).